FASTKD5 (FAST kinase domains 5)
Description:
Required for the processing of non-canonical mitochondrial pre-mRNAs within the primary mitochondrial polycistronic transcript, i.e. pre-mRNA sequences that are not flanked by tRNA (tRNA punctuation). Has endoribonuclease activity and processes MT-CO1, MT-CO3 and MT-CYB pre-mRNAs, generating products with 3'/2'-phosphate or a 2',3'-cyclic phosphodiester at the 3'-end.
Synonyms: FLJ13149; MC4DN24; dJ1187M17.5
Tractability: PROTAC: ubiquitination databases record sites on it; its protein half-life has been measured.
Gene: Protein-coding gene on chromosome 20 (3,146,519 to 3,159,865, reverse strand). Ensembl gene ENSG00000215251.
Subcellular location: Mitochondrion matrix, mitochondrion nucleoid
Pathways (Reactome):
Metabolism of RNA: FASTK family proteins regulate processing and stability of mitochondrial RNAs
Gene Ontology:
Molecular function: protein binding; RNA binding; RNA endonuclease activity; rRNA binding
Biological process: mitochondrial polycistronic RNA processing; mitochondrial RNA processing; regulation of mitochondrial mRNA stability
Cellular component: mitochondrial nucleoid; mitochondrion; ribonucleoprotein granule; mitochondrial matrix
Genetic constraint (gnomAD): Loss-of-function variants: 33 observed, 48.2 expected, observed/expected ratio (o/e) 0.68, 90% interval 0.52 to 0.92. The upper end of that interval is the gene's LOEUF score, 0.92, which puts it in group 3 of 6, group 1 being the genes least tolerant of losing a copy. Missense variants: 868 observed, 960.56 expected, observed/expected ratio (o/e) 0.9, 90% interval 0.85 to 0.96. Synonymous variants: 335 observed, 362.58 expected, observed/expected ratio (o/e) 0.92, 90% interval 0.84 to 1.01.
Homologues: Orthologues: macaque FASTKD5 (95% identical), pig FASTKD5 (79% identical), dog FASTKD5 (76% identical), rat Fastkd5 (75% identical), mouse Fastkd5 (74% identical), guinea pig FASTKD5 (72% identical), tropical clawed frog fastkd5 (47% identical). Paralogues in human: FASTKD3 (15% identical), TBRG4 (15% identical), FASTKD1 (14% identical), FASTKD2 (13% identical), FASTK (11% identical).
Diseases named in the same sentence as FASTKD5 in open-access papers:
FASTKD5 is named in the same sentence as 3 diseases in open-access papers, as found by Europe PMC text mining. Sharing a sentence is not in itself a finding about the gene and the disease. The quoted sentences say what the papers report.
HIV-1 infection (2 papers, 2022). The type species of lentivirus and the etiologic agent of acquired immunodeficiency syndrome (AIDS). "A recent study demonstrated that two mitochondria-localized proteins (NLRX1 and FASTKD5) mediate OxPhos upregulation during HIV-1 infection of CD4+ T cells, promoting viral replication, thus uncovering a novel and interesting regulatory axis for therapeutic targeting against HIV-1 infection." (PMID 35205318, 2022).
melanoma (1 paper, 2020). A malignant, usually aggressive tumor composed of atypical, neoplastic melanocytes. "Among these kinases, 6 (RPS6KB2, DSTYK, TBRG4, CDK4, POLR2E, FASTKD5) and 4 (STK26, PAK1, EPHB2 and JAK3) were consistently up- or down-regulated, respectively, in the metastatic lines of at least two pairs of melanoma cells." (PMID 32051510, 2020).
cancer (1 paper, 2021). A tumor composed of atypical neoplastic, often pleomorphic cells that invade other tissues. "FASTKD1, FASTKD3 and FASTKD5 were the FASTK genes most frequently mutated in cancers." (PMID 34768773, 2021). "These interesting results not only reveal the known relationship of FASTK proteins to mitochondrial physiology, but also uncover the particular interaction of FASTK, FASTKD2, FASTKD4 and FASTKD5 with cancer signaling pathways." (PMID 34768773, 2021). "Finally, the protein-protein interaction network for FASTK proteins uncovers the interaction of FASTK, FASTKD2, FASTKD4 and FASTKD5 with cancer signaling pathways." (PMID 34768773, 2021). "Finally, we provide novel evidence of the PPI network of FASTK proteins, which uncovers the interaction of FASTK, FASTKD2, FASTKD4 and FASTKD5 with cancer signaling pathways." (PMID 34768773, 2021). "To date, there are no studies that describe altered expression of FASTKD4 or FASTKD5 in cancer." (PMID 34768773, 2021).